ACSL4 (acyl-CoA synthetase long chain family member 4)
Diseases named in the same sentence as ACSL4 in open-access papers (continued):
Sharing a sentence is not in itself a finding about the gene and the disease.
glioma (46 papers, 2020 to 2026). A benign or malignant brain and spinal cord tumor that arises from glial cells (astrocytes, oligodendrocytes, ependymal cells). "Elevated temperatures stabilize Acsl4 expression, inducing ferroptosis in glioma cells, as well as causing alterations in mitochondrial morphology and membrane potential." (PMID 38915336, 2024). "Therefore, we suspected that glioma cells transfected with HSP27 lentivirus are associated with a SUMO-related association with ACSL4." (PMID 36639654, 2023). "Our general assumption was that GBM might escape ferroptosis via genetic deficiency of Acsl4, which is essential for glioma lipidomics and serves as a vital ferroptosis marker in glioma." (PMID 35697672, 2022). "It was revealed that reduced ferroptosis in human glioma tissue and glioma cells might be associated with ACSL4, an important molecule in the emergence of ferroptosis." (PMID 36091118, 2022). "Additionally, a recent study has directly linked the enzymatic activity of ACSL4 to the induction of ferroptosis and the subsequent suppression of the proliferation of several glioma cell lines." (PMID 36012521, 2022). "Hsp90 dephosphorylates Drp1 at the Ser637 site, promoting glioma ferroptosis by enhancing ACSL4-dependent lipid peroxidation." (PMID 40756764, 2025). "The literature suggests that miR‐670‐3p is a tumor suppressor, as has been shown to reduce glioma growth by targeting ACSL4, essential for ferroptosis." (PMID 39229655, 2024). "For instance, it has been discovered to promote ferroptosis in NSCLC by modulating SLC7A11/GPX4, and it can induce ferroptosis in glioma cells by the ACSL4/GPX4 pathway, thus providing antitumor benefits." (PMID 39266965, 2024). "ACSL4 was shown to be significantly downregulated in gliomas, and low expression of ACSL4 reduced ferroptosis sensitivity and increased glioma cell viability." (PMID 38590315, 2024). "Nonetheless, activated HIF2a by Roxadustat improves several lipid-related genes, including ACSL4, and unexpectedly evokes ferroptosis in gliomas, which calls for further exploration." (PMID 39309434, 2024). "Heat shock protein 90 (Hsp90) and dynamin-related protein 1 (Drp1) actively regulate and stabilize ACSL4 expression during ferroptosis in glioma triggered by erastin." (PMID 36937406, 2023). "Depletion of ACSL4 has been reported to inhibit ferroptosis in multiple cancer cells including glioma cells." (PMID 37158834, 2023). "For instance, capsaicin, as a potential anticancer ferroptosis inducer, suppresses the proliferative effects of glioma cells by increasing ACSL4 levels and decreasing GPX4 levels to induce ferroptosis." (PMID 36358495, 2022). "Subsequently, some targeting molecular mechanisms had been put up based on ACSL4, which shed light on the treatment of glioma." (PMID 36507355, 2022). "Hitherto, Acsl4 has rarely been mentioned in gliomas, thus further research is required to understand its role in this malignancy." (PMID 35697672, 2022). "ACSL4 down-regulates glioma cell proliferation and mediates up-regulation of ferroptosis levels in gliomas." (PMID 36091118, 2022). "Patient-derived glioma samples present with a lower expression of both ACSL4 and ACSL6 compared to normal tissue, likely to mitigate the production of pro-apoptotic ceramides." (PMID 36012521, 2022). "In the present study, researchers found that ACSL4 promoted ferroptosis in glioma cells and functioned with anti-proliferative effects." (PMID 36497375, 2022). "Dihydrotanshinone I (DHI) can inhibit the proliferation of human glioma cells via the induction of ferroptosis, while capsaicin can induce ferroptosis through the increase in expression of ACSL4." (PMID 36507355, 2022). "In this study, we demonstrated that heat shock protein 90 (Hsp90) and dynamin-related protein 1 (Drp1) actively regulated and stabilized Acsl4 expression in erastin-induced ferroptosis in gliomas." (PMID 35697672, 2022).
glioma (continued). "Transfection of shAcsl4 or Acsl4 overexpression plasmids into two primary glioma cell lines, PL1 and PG7, confirmed the role of Acsl4 in glioma ferroptosis." (PMID 35697672, 2022). "Dihydrotanshinone I (DHI), which boosted ferroptosis by decreasing the expression level of GPX4 and increasing that of ACSL4, inhibited the growth and proliferation of glioma cells." (PMID 36358495, 2022). "Acyl–coenzyme A (CoA) synthetase long-chain family member 4 (Acsl4), a pivotal enzyme in the regulation of lipid biosynthesis, benefits the initiation of ferroptosis, but its role in gliomas needs further clarification." (PMID 35697672, 2022). "Overall, Drp1 dephosphorylating at Ser637 reduced mitochondrial filamentation, which was essential for Acsl4-dependent ferroptosis in glioma cells." (PMID 35697672, 2022). "Recent studies have indicated that Acsl4 is downregulated in glioma, where it has anti‐proliferative effects." (PMID 35429110, 2022). "After treatment of human glioma cells with dihydrotanshinone I, GPX4 expression decreased while ACSL4 expression increased, inducing ferroptosis in human glioma cells." (PMID 36091118, 2022). "Our study uncovered an important role of Acsl4 in predicting patient prognosis due to its high inducibility in glioma ferroptosis." (PMID 35697672, 2022). "This study found ACSL4 expression was decreased in glioma cells and reduced expression of ACSL4 compared to the normal human brain." (PMID 36091118, 2022). "In this study, we demonstrated that Acsl4 was highly inducible following erastin treatment of glioma cells." (PMID 35697672, 2022). "Studies in human glioma have found that ACSL4 expression is down-regulated and iron death is also reduced." (PMID 35126480, 2022). "The siRNA-mediated silencing of ACSL4 promoted the proliferation in glioma cells via the decrease in ferroptosis through the enhancement of GPX4 expression." (PMID 32656078, 2020). "All these results suggest that ACSL4 inhibition directly affects the expression of GPx4, which finally promotes glioma cell proliferation by inhibiting ferroptosis." (PMID 32656078, 2020). "Further, ACSL4 regulation can be influenced by cellular stress pathways: in glioma cells, heat shock protein Hsp90 and dynamin-related protein 1 (Drp1) dephosphorylation stabilize ACSL4 expression during erastin-induced ferroptosis, promoting mitochondrial fragmentation and lipid peroxidation." (PMID 41516398, 2026). "For example, ACSL4 inhibits glioma proliferation by activating ferroptosis in tumor cells." (PMID 40050614, 2025). "In glioma cells, knockdown of ACSL4 inhibited glioma cell ferroptosis and promoted tumor growth." (PMID 38503553, 2024). "It has been demonstrated that gliomas notably reduce ACSL4 expression." (PMID 39309434, 2024). "Concurrently, HSP90 stabilizes Acsl4 expression, thereby facilitating ferroptosis in glioma cells." (PMID 38915336, 2024). "Given the mitochondrion is a main organelle for cellular oxidative phosphorylation and ROS production, we wished to unambiguously determine whether mitochondria were affected in Acsl4-dependent ferroptosis in glioma cells." (PMID 35697672, 2022). "ACSL4 was found to be downregulated in only one of the glioma cell lines, A172." (PMID 36142793, 2022). "Besides, in erastin-induced ferroptosis in gliomas, heat shock protein 90 (Hsp90) and dynamin-related protein 1 (Drp1) were reported to actively stabilize and regulate ACSL4 expression." (PMID 36507355, 2022). "Moreover, past studies have demonstrated that overexpression of acyl-CoA synthetase long-chain family member 4 (ACSL4) results from ferroptosis induction, yielding a remarkable effect on inhibiting glioma cell proliferation." (PMID 35912242, 2022). "ASCL4 was considered as a sensitive monitor as well as an important contributor of ferroptosis and eliminated the inhibition of GPX4 on ferroptosis in osteosarcoma cells, and overexpression of ACSL4 in glioma significantly reduced GPX4 level and contributes to ferroptosis." (PMID 36407113, 2022).
glioma (continued). "Therefore, ACSL4 is proposed to protect glioma cells and play an anti-proliferative role by activating the ferroptosis pathway, and highlights the key role of ACSL4 in regulating ferroptosis in the protection of glioma." (PMID 35126480, 2022). "The results demonstrated that Acsl4 could be the component that differentiates ferroptotic sensitivity between different grades of gliomas." (PMID 35697672, 2022). "In our study, we found that Hsp90-dependent Drp1 dephosphorylation promoted Acs4 expression by binding and stabilizing Acsl4, which could sensitize glioma cells to erastin-induced ferroptosis." (PMID 35697672, 2022). "Studies have shown that ACSL4 expression is down-regulated after glioma occurs." (PMID 36091118, 2022). "Additionally, we also detected the protein levels of Acsl4 among various glioma cell lines such as U87, U251, T98, PL1, and PG7, in contrast with normal human astrocytes (NHAs) in culture." (PMID 35697672, 2022). "ACSL4 suppresses glioma cell proliferation via activating ferroptosis." (PMID 34531924, 2021). "ACSL4, a key mediator of ferroptosis, has also shown decreased expression in gliomas." (PMID 34944434, 2021). "In gliomas, ACSL4 can inhibit the proliferation of tumor cells by activating ferroptosis." (PMID 33330074, 2020). "A convey revealing the relationship between ferroptosis-related genes (FRGs) and gliomas indicated that interferon regulatory factor 2 (IRF2) was positively associated with glioma grade and contributed to gliomas, potentially by maintaining low ACSL4 level and high xCT/GPX4 level." (PMID 39309434, 2024). "The new discovery suggests that the HSP27/SUMO/ACSL4 axis may inhibit glioma by ferroptosis." (PMID 36639654, 2023). "Furthermore, their speculates confirmed that ACSL4 plays an essential role in regulating ferroptosis and proliferation in glioma cells and knocking down the gene significantly improved the viability of glioma cells." (PMID 36091118, 2022). "Herein, we described an underlying mechanism for the regulation of ferroptosis between different grades of gliomas: LGGs could have a considerable effect on the decision-making because ferroptosis was more likely to happen in LGGs due to the high Acsl4 expression levels of LGGs." (PMID 35697672, 2022). "Therefore, ACSL4 and 6 may contribute to the increased C18–24 ceramide levels observed in IDHmut gliomas, contributing to their metabolic vulnerabilities." (PMID 36012521, 2022). "However, in the recurrent glioma, the expression of ACSL4 was found significantly increased, indicating glioblastoma relapses may be higher vulnerable to ferroptosis." (PMID 36507355, 2022). "Therefore, we concluded that the mitochondrion was a primary site of Acsl4-dependent ferroptosis in glioma cells and that mitochondrial morphology could be affected by expression of Acsl4 in glioma ferroptosis." (PMID 35697672, 2022). "Next, we examined whether Hsp90 could sensitize glioma cells to Acsl4-dependent ferroptosis." (PMID 35697672, 2022). "We demonstrate that boric acid modulates the SOX10/GPX4/ACSL4 axis, elucidating the involvement of SOX10 signalling in ferroptosis within glioma cells." (PMID 40159622, 2025). "Therefore, ACSL4 may serve as a novel therapeutic target in glioma treatment." (PMID 36497375, 2022). "The decrease in the expression level of ACSL4 has been observed in isocitrate dehydrogenase (IDH) 1 wild-type and mutant gliomas." (PMID 36507355, 2022). "Given that Acsl4 showed the highest upregulation in LGG1 and the highest downregulation in GBM7, we selected patient-derived glioma cells PL1 and PG7 for subsequent experiments, which were respectively isolated from discarded LGG1 and GBM7 specimens." (PMID 35697672, 2022). "In general, the ACSL4/GPX4 pathway can inhibit the proliferation of glioma cells by activating ferroptosis, thus providing a new idea for the treatment of glioma." (PMID 34944434, 2021).
glioma (continued). "Therefore, ACSL4 may also regulate TMZ resistance in gliomas by affecting the GPX4 expression." (PMID 32656078, 2020). "The LDA results revealed a significantly increased expression of iron metabolism-related genes ferritin heavy chain 1 (FTH1), transferrin receptor (TFRC), and Acyl-CoA synthetase long-chain family member 4 (ACSL4), while GPX4 expression was decreased in the glioma samples compared to the controls." (PMID 41154694, 2025). "Metformin can mainly inhibit GPX4 protein expression in glioma cells, promote the expression of Long-chain acyl-CoA synthetase 4 (ACSL-4) protein, which leads to the increase of Reactive Oxygen Species(ROS) level, triggers ferroptosis, and inhibits glioma proliferation." (PMID 39944825, 2025). "However, in glioma, HSP90 binds to calcineurin and stimulates its activity, promotes the dephosphorylation of DRP1 at SER637, further binds to and stabilizes ACSL4, and ultimately sensitizes cells to ferroptosis." (PMID 40083691, 2025). "Moreover, this study is the first to establish a link between SOX10 overexpression in glioma cells and its involvement in ferroptosis signalling, specifically through the GPX4/ACSL4 axis in U87 cells." (PMID 40159622, 2025). "ACSL4 overexpression was found to decrease GPX4 overexpression and increase ferroptosis marker levels, such as 5-hydroxyeicosatetraene (5-HETE), 12-HETE and 15-HETE, in glioma cells." (PMID 36937406, 2023). "Specifically, DHA could promote the development of ACSL4 and xCT, but significantly downregulated GPX4 levels, initiating the death of glioma cells by maintaining ferroptosis." (PMID 36358495, 2022). "After overexpression of ACSL4, the GPX4 expression was significantly reduced, whereas the expression of ferroptosis indicators 5-HETE, 12-HETE, and 15-HETE significantly increased, thus inhibiting the proliferation of glioma cells." (PMID 34944434, 2021). "On the other hand, overexpression of ACSL4 was shown to increase the levels of ferroptosis markers, including 5-hydroxyeicosatetraenoic acid (HETE), 12-HETE, and 15-HETE, indicating a key role of ACSL4 in regulating ferroptosis and proliferation of glioma cells." (PMID 36591531, 2022).
colorectal cancer (44 papers, 2016 to 2025). A primary or metastatic malignant neoplasm that affects the colon or rectum. "Present studies have demonstrated that the ACSL4 dysregulation is associated with the progression of many malignant tumors, including gastric cancer, prostate cancer, and colorectal cancer." (PMID 34458145, 2021). "ACSL1 and ACSL4 overexpression was associated with a poor clinical outcome in stage II colorectal cancer patients." (PMID 33030783, 2020). "Inhibiting ACSL4 methylation mediated by coactivator-associated arginine methyltransferase 1 enhances ferroptosis in colorectal cancer, where prohibiting cyclin-dependent kinase 1 also alleviates resistance to oxaliplatin by modulating ACSL4-mediated ferroptosis." (PMID 39935430, 2025). "In addition, a higher ACSL4 level was reported to be associated with a poorer prognosis in colorectal cancer and was correlated with shorter survival and DFS in HCC." (PMID 39335604, 2024). "Moreover, in colorectal cancer cells, ACSL4 overexpression and, to a lesser extent ACSL1, cause a shift of energy metabolism towards glucose utilization." (PMID 31344914, 2019). "The network of ACSL1, ACSL4 and steraroyl-CoA desaturase-1 (SCD), which catalyzes the conversion of SFA into MUFA, is demonstrated to induce EMT program and the higher expression level of ACSL1/ACSL4/SCD is associated with the poorer survival outcome in colorectal cancer." (PMID 27171439, 2016). "Elevated ACSL4 correlates with increased ferroptosis sensitivity and enhanced invasiveness in cancers such as colorectal cancer." (PMID 39935430, 2025). "In colorectal cancer, ACSL4 promotes lipid peroxidation and ferroptosis in tumor cells and confers sensitivity to oxaliplatin." (PMID 40050614, 2025). "YAP promotes ferroptosis in colorectal cancer by transcriptionally upregulating acyl-CoA synthetase long-chain family member 4 (ACSL4) and transferrin receptor (TFRC) expression." (PMID 40619484, 2025). "In particular, 3,5-di-caffeoylquinic acid, a MO component, suppresses mitochondrial dysfunction and ferroptosis by regulating the expression of GPX4, ACSL4, and xCT in colorectal cancer cells." (PMID 40365315, 2025). "Accumulating evidence has confirmed that ACSL4 can enhance the sensitivity of cancer cells to drug treatment by promoting ferroptosis, such as renal cell carcinoma and colorectal cancer." (PMID 39039611, 2024). "The results showed that compared with KRAS wild-type colorectal cancer cell line, KRAS mutant colorectal cancer cell line showed significant upregulation of ACSL4." (PMID 35910359, 2022). "The patients with high expression of ACSL4 have poor prognosis in colorectal cancer (OS: total number, 177; 95% CI, 1.36–3.28, HR, 2.11; Cox P, 0.000896,433; DSS: total number, 177; 95% CI, 1.19–3.25, HR, 1.96; Cox P, 0.00877,945)." (PMID 35126480, 2022). "In previous studies, Park et al37 found that ACSL4 levels are high in K‐RAS mutant colorectal cancer cells, which are sensitive to ferroptosis." (PMID 33314758, 2021). "Bromelain was shown to induce ferroptotic cell death in KRAS-mutant colorectal cancer wherein bromelain increased the level of long-chain acyl-CoA synthetase-4 (ACSL4) an isozyme which plays role in lipid biosynthesis and fatty acid degradation." (PMID 33435480, 2021). "Bromelain exerted cytotoxic effects in Kras-mutant colorectal cancer cells via downregulating acyl-CoA synthetase long-chain family member 4 (ACSL4) to induce ferroptosis." (PMID 34046350, 2021). "Conversely, the shRNA-mediated knockdown of ACSL1 or ACSL4 reduces cell proliferation in colorectal cancer cell lines, with a more marked effect elicited by the ACSL4 knockdown." (PMID 31344914, 2019). "Compared to the Kras wild-type colorectal carcinoma cell lines, Kras mutant colorectal carcinoma cell lines exhibited a remarkably up-regulated expression of ACSL-4, which is responsible for ferroptosis sensitivity." (PMID 30460115, 2018).